SMAD3 (SMAD family member 3)
Diseases named in the same sentence as SMAD3 in open-access papers (continued):
Sharing a sentence is not in itself a finding about the gene and the disease.
pulmonary fibrosis (continued). "Moreover, miR-3934-3p have been found to down-regulate TGFBR1 and SMAD3 which are critical players for lung fibrosis and have been previously reported in SARS-CoV-related cases." (PMID 37053191, 2023). "In previous studies, PFD ameliorates pulmonary fibrosis by inhibiting the TGF‐β1/Smad3 pathway." (PMID 35861038, 2022). "Taken together, these results indicated that PIC may improve pulmonary fibrosis by enhancing autophagy via inhibiting the Smad3/ERK/P38 signaling pathway." (PMID 35747752, 2022). "Collectively, our findings demonstrate that fibroblast PD-L1 may promote pulmonary fibrosis through both Smad3 and β-catenin signaling and may represent a novel interventional target for IPF." (PMID 35197539, 2022). "HMGA2 (High-mobility group AT-hook 2) is a transcription factor that is induced by the TGF-β1/Smad3 signaling pathway and is also reported to be upregulated in pulmonary fibrosis and inhibit bleomycin-induced pulmonary fibrosis." (PMID 35980387, 2022). "ERK1/2 and TGFβ1/Smad3 are two key signaling pathways that are involved in pulmonary fibrosis." (PMID 33747104, 2021). "However, ROS can also increase the level of connective tissue growth factor and matrix metalloproteinases by regulating the TGF-β1/Smad3 signaling pathway and promoting extracellular matrix remodeling and pulmonary fibrosis." (PMID 33763150, 2021). "At present, the signal transduction pathways of TGF-β1 are mainly classified into Smad protein-dependent and -independent signaling and the TGF-β1-induced Smad3 signaling pathway has been considered to be one of the most important mechanisms of pulmonary fibrosis progression." (PMID 33549109, 2021). "In this study, we showed that CRBN deficiency may suppress the development of BLM-induced pulmonary fibrosis in mice in vivo and inhibit the TGF-β1-induced activation of lung fibroblasts in vitro by suppressing SMAD3 phosphorylation." (PMID 34002012, 2021). "The mechanism of EndMT and the upregulated lncRNA Gm16410 was further investigated and it was found that lncRNA Gm16410 mediates PM2.5‐induced EndMT by regulating the TGF‐β1/Smad3/p‐Smad3 pathway, which highlights the potential of lncRNAs to promote pulmonary fibrosis under environmental pollution." (PMID 33533071, 2021). "The potential mechanism of the protective effects of curdione on pulmonary fibrosis might be attributed to the inhibition of TGF-β/Smad3 signaling." (PMID 32075634, 2020). "TGFβ1/Smad3 signal pathway plays an important role in lung fibrosis and epithelial regeneration." (PMID 33101446, 2020). "The results show that collagen metabolism imbalance, inflammatory response, and epithelial-mesenchymal transition (EMT) are the core processes in IPF, and the TGF-β1/Smad3 and Wnt/β-catenin pathways are the key signaling pathways for the development of pulmonary fibrosis." (PMID 33584272, 2020). "TGF-β/Smad3 signaling plays a critical role in the development of pulmonary fibrosis." (PMID 33381023, 2020). "However, another study on lung fibroblasts has found that Cyr61 affects TGF-β1/SMAD3 signaling pathway and promotes pulmonary fibrosis." (PMID 31130867, 2019). "Paeonol has therapeutic functions on BLM-induced pulmonary fibrosis in mice and, at least in part, could be mediated by the inhibition of the MAPKs/Smad3 signaling pathway." (PMID 31354856, 2019). "Pulmonary TGF-β/Smad3 signaling was activated in BLM-induced lung fibrosis." (PMID 31775746, 2019). "This study is the first investigation to demonstrate that the Smad3 gene might participate in the development of pulmonary fibrosis in Uygur PBL via increased mRNA expression induced by hypomethylation." (PMID 28562330, 2017). "Analysis of the putative promoter sequence by the Genomatix algorithm revealed a binding site for Smad3 in the upstream region of the miR-26a gene, suggesting a novel autoregulatory loop between miR-26a and phosphorylated Smad3 in the context of pulmonary fibrosis." (PMID 29186838, 2017).
pulmonary fibrosis (continued). "Smad3 gene methylation level was strongly correlated with Smad3 mRNA expression (correlation coefficient: -0.84), whereas the extent of pulmonary fibrosis was weakly correlated with the Smad3 gene methylation level and Smad3 mRNA expression (correlation coefficients: -0.18 and 0.21, respectively)." (PMID 28562330, 2017). "After constructing a genomic methylation analysis for patients with PBL and detecting abnormal Smad3 gene hypomethylation, we hypothesized that pulmonary fibrosis in patients with PBL is correlated with Smad3 gene methylation." (PMID 28562330, 2017). "Smad3 gene hypomethylation might promote pulmonary fibrosis in Uygur PBL patients via increased Smad3 mRNA expression." (PMID 28562330, 2017). "Overall, our data indicate that the CHRF-miR-489-MyD88 Smad3 signaling axis exerts key functions in silica-induced pulmonary fibrosis and may represent a therapeutic target for silicosis." (PMID 27506999, 2016). "Finally, using an adenoviral TGFβ1 over-expression model of pulmonary fibrosis we demonstrate that Smad3 is crucial for TGFβ1-induced αvβ6 integrin expression within the alveolar epithelium in vivo." (PMID 27494713, 2016). "Moreover, our results reveal that miR-140 overexpression increases the sensitivity of AECs to PTX, but more precise mechanisms of cooperation of PTX and miR-140 in suppressing TGF-β1/Smad3-induced pulmonary fibrosis need further study." (PMID 23967091, 2013). "Therefore, the effect of PTX on TGF-β1/Smad3 pathway was studied to explore the mechanism of PTX in relieving of pulmonary fibrosis." (PMID 23967091, 2013). "Smad3 and p-Smad3 are involved in TGF-β1-induced fibrotic gene responses as well as in BLM-induced pulmonary fibrosis, p-Smad3 is responsible for TGF-β1 fibrosis activation and alpha-smooth muscle actin (α-SMA) is one of the key indicators of fibrotic lung diseases." (PMID 23967091, 2013). "Furthermore, continuous exposure of Smad3−/− mice to Osm induced severe sub-epithelial and interstitial pulmonary fibrosis 14 days later that was comparable to the response seen in wild-type mice." (PMID 22684844, 2012). "Moreover, lncRNA H19 knockdown could reduce the progression of pulmonary fibrosis via the lncRNA H19-miR-140-TGF-β/Smad3 regulatory network, suggesting that lncRNA H19 may serve as an early diagnostic and prognostic biomarker for pulmonary fibrosis." (PMID 35289324, 2022). "Similarly, in a bleomycin-induced experimental ALI in mice, CCN1 expression was found to be elevated in the alveolar mesenchymal cells, which in turn, activated the TGF-b1/SMAD3 pathway-dependent profibrotic signaling that contributed to ALI-mediated pulmonary fibrosis." (PMID 33105556, 2020). "Smad proteins are the main signal transducers for TGF-β1 signaling pathway, in which Smad3 binds to Smad 4 to form a complex and then make an entry into the nucleus in order to regulate the targeted gene transcription, which thereby interfere with the formation of lung fibrosis." (PMID 30719057, 2019). "Smad3 may be a central TGFβ1 signalling intermediate in the pathogenesis of pulmonary fibrosis." (PMID 27494713, 2016). "In addition, he had idiopathic pulmonary fibrosis, which has not been associated with SMAD3 in humans." (PMID 26257771, 2015). "Because EMT induced by TGF-β1 is a key issue in the pathogenesis of tissue or organ fibrosis and inhibition of TGF-ß1 or Smad 2/3 could reverse EMT in hepatic fibrogenesis, drugs or targets of TGF-β/Smad3 pathway might be a suitable approach for pulmonary fibrosis therapy." (PMID 23967091, 2013). "In gp130wt mice, however, ablation of Smad3 (Smad3−/−) reduced bleomycin-dependent lung fibrosis in mice as previously reported when compared to the fibrotic lesions and excessive collagen deposition observed in Smad3 proficient wild-type mice 30 days after bleomycin challenge." (PMID 22684844, 2012). "Importantly, knockdown of the TGFβ1/Smad3 signaling pathway inhibits experimental lung fibrosis." (PMID 22997505, 2012).
pulmonary fibrosis (continued). "Because phosphorylation of Smad signaling by the activated TGFβ1 receptor I is a major step in the initiation of TGFβ1 signal transduction, we further examined whether Smad2 and Smad3 phosphorylation in bleomycin-induced pulmonary fibrosis was changed by AG treatment." (PMID 19552800, 2009). "Western blot analysis of the lung tissues found that the levels of pulmonary fibrosis markers including α-SMA, p-Smad3 and Fn1 were higher in RTN3-null group than in Wild type group after bleomycin treatment." (PMID 39972424, 2025). "In this study, EPM administration suppressed fibrosis-related markers, including TGF-β1, p-Smad3, Collagen III, α-SMA, and MMP-9, while upregulating antifibrotic mediators such as TIMP-1, thereby reducing the MMP-9/TIMP-1 ratio and mitigating lung fibrosis." (PMID 40507891, 2025). "For instance, artemisinin has been found to inhibit myofibroblast growth and reduce bleomycin-induced pulmonary fibrosis by downregulating pro-fibrotic proteins such as TGF-β1, Smad3, HSP47, α-SMA, and collagen type I." (PMID 40761396, 2025). "In PF, HSPB1 regulates TGF-β-mediated lung fibroblast differentiation via the Smad3 and ERK pathways and contributes to radiation-induced lung fibrosis via the activation of the IkBα-NFκB signaling." (PMID 39863585, 2025). "For instance, Salvianolic acid B was shown to attenuate paraquat-induced pulmonary fibrosis by restoring the Nrf2/NOX4 redox balance, where Nrf2 activation suppressed NOX4 expression and downstream TGF-β1/Smad3 signaling." (PMID 40438605, 2025). "LncNEAT1 is identified as a sponge for miR-9-5p and miR-455-3p, respectively, which promotes pulmonary fibrosis by regulating the miR-9-5p/TGF-β1/Smad2 and miR-455-3p/Smad3 axes." (PMID 39479511, 2024). "Concurrently, the activation of the TGF-β1/SMAD3 and HIF-1 signaling pathways expedites the EMT of alveolar type 2 epithelial cells, thereby advancing the progression of lung fibrosis." (PMID 39193364, 2024). "In a silica-induced pulmonary fibrosis mouse model, CHRF activates inflammatory and fibrotic pathways via the miR-489/MyD88 and miR-489/SMAD3 axes, with SMAD3 being an adaptor in receptor-regulated signaling." (PMID 38473915, 2024). "It has been reported that the EndoMT in HPMECs mediated by the TGF-β1/Smad3 pathway, and the EMT in lung epithelial cells can contribute to the development of COPD and pulmonary fibrosis." (PMID 39108691, 2024). "Through direct targeting of Smad4, miR-26a inhibits the nuclear translocation of p-Smad3, thereby blocking TGF-β1 downstream signal transduction and mitigating pulmonary fibrosis." (PMID 39479511, 2024). "In conclusion, PRXT mediates the inhibition of GRK2, which further blocks the transcription of Smad3 in TGF-β1-induced lung fibroblasts, providing an attractive therapeutic target for pulmonary fibrosis." (PMID 37815883, 2023). "In Smad3-KO mice, TGF-β cannot induce EMT and the key transcription factors of fibrosis, leading to a weakened pulmonary fibrosis phenotype." (PMID 37268886, 2023). "Hesperidin also lessens BLM-induced pulmonary fibrosis by inhibiting the IB/NF-kB,/ TGF-1/MPK, Smad3, and oxide-inflammatory marker (HO-1 and Nrf2) pro-inflammatory marker (IL-1, TNF-α, and IL-6) pathways." (PMID 37109466, 2023). "In conclusion, avitinib alleviates bleomycin-induced pulmonary fibrosis and inhibits lung fibroblast activation, migration and ECM accumulation by inhibiting TGF-β1/Smad3 signalling." (PMID 36949426, 2023). "In our study we identified that, in the context of lung fibrosis, the inhibition of HSPB5 by NCI-41356 interfered with the TGF-β1 pathway through SMAD3/4." (PMID 37259327, 2023). "Moreover, Smad3‐deficient mice do not develop pulmonary fibrosis." (PMID 37723905, 2023). "TGF-β1/SMAD3 directly promoted the transcription of HDAC3, which aggravated EMT in AT2 and pulmonary fibrosis in mice via deacetylation of GATA3 and inhibition of its degradation." (PMID 37951958, 2023).
pulmonary fibrosis (continued). "In the context of IPF and bleomycin-induced lung fibrosis, CD274 induction plays a role in the SMAD3/GSK3-mediated fibroblast to myofibroblast fate induction and collagen deposition, and in the IPF fibroblasts’ invasive properties." (PMID 35626630, 2022). "Pulmonary TGF-β1 levels are increased in a model of experimental lung fibrosis, and TGF-β1 overexpression induces persistent pulmonary fibrosis via the SMAD3 signaling pathway." (PMID 33987189, 2021). "Inhibition of TGF-β signaling through knockout of Smad3, the key mediator of TGF-β canonical pathway, successfully abolishes pulmonary fibrosis induced by high-fat diet." (PMID 35082682, 2021). "Smad 3 is indispensable for these processes, and Smad3-knockout mice are resistant to TGF-β- and bleomycin-mediated lung fibrosis." (PMID 34222222, 2021). "Smad3 and Smad4 proteins were overexpressed in BLM-induced pulmonary fibrosis rats compared with normal rats." (PMID 33953686, 2021). "Consistently, overexpression of miR-221 in these cell lines suppresses HMGA2 as well as phosphorylated-Smad3, which modulate TGF-β1 signaling, and leads to attenuation of EMT and lung fibrosis." (PMID 34819948, 2021). "On the contrary, Smad7 inhibits pulmonary fibrosis by competitively binding to TGF-β and its receptors complex with Smad3." (PMID 33953686, 2021). "It has been demonstrated that SARS-CoV N protein potentiate Smad-3 mediated TGF-β activation, and plasminogen activator inhibitor-1 (PAI-1), leading to severe pulmonary fibrosis and inactivation of pro-apoptotic genes by complex formation of Smad3 and Smad4." (PMID 32512929, 2020). "A link between PGE2 production and TGF-β, the most important cytokine involved in the induction of lung fibrosis has been suggested; in fact naproxen down-regulates TGF-β levels and Smad3/4 complex formation." (PMID 32927723, 2020). "TβRI mediates the nuclear localization of Smad3, the induction of α-SMA during the collagen-induced EMT of alveolar epithelial cells, and fibroblast accumulation during idiopathic pulmonary fibrosis (IPF)." (PMID 33343360, 2020). "Taken together, FIS can alleviate the development of BLM-induced pulmonary fibrosis, which is related to the inhibition of TGF-β/Smad3 signaling and the reduction of alveolar epithelium cell senescence by regulating AMPK/NF-κB signaling pathway." (PMID 33381023, 2020). "We also found that the inhibitory action of TAF on the TGF-β1/Smad3 pathway resulted from enhancement of NS5ATP9, suggesting that NS5ATP9 plays an important role in pulmonary fibrosis." (PMID 31331325, 2019). "BLM promotes the development of inflammation, which results in severe pulmonary fibrosis and increased TGF-β1, Smad3, and signal transducer and activator of transcription (STAT)." (PMID 30092799, 2018). "Accordingly, the compound HSc025 inhibits Smad3 activation and downstream gene regulation, including collagen and fibronectin, in vitro, whereas in vivo administration in mice could protect from bleomycin-induced lung fibrosis or from sclerotic skin development." (PMID 29701666, 2018). "Subsequent Shenks treatment led to a lower phosphorylation level of Smad3 (40.0% lower, P < 0.001), indicating that Shenks treatment alleviated the abnormal activation of the TGF-β pathway in pulmonary fibrosis." (PMID 28533545, 2017). "Inhibition of MAPK7 blocked the TGF-β1 signal for Smad3 transcriptional activity via acetylation and regulated TGF-β1-induced pulmonary fibrosis." (PMID 29084594, 2017). "In our study, OVA-induced mice exhibited pulmonary fibrosis, resulting in the overexpression of TGF-β1/Smad-3 and deposition of collagen." (PMID 27741312, 2016). "Further, AG treatment also decreased BLM-induced HSP47 expression, downregulated TGFβ1, p-Smad2 and p-Smad3 expressions, and subsequently attenuated BLM-induced pulmonary fibrosis." (PMID 19552800, 2009).
pulmonary fibrosis (continued). "Pulmonary fibrosis (PF) from cigarette smoke is partly due to subsequent enrichment of HBE exosomes with miR-21, which, when taken up by fibroblasts, modulates the TGF-β1/Smad3 pathway to increase collagen and α-SMA expression." (PMID 40676634, 2025). "Notably, human PAPCs from idiopathic pulmonary fibrosis (IPF) showed reduced CLIC4 and SMAD3-target genes expression compared to PAPCs from normal lungs." (PMID 39448571, 2024). "In mice with pulmonary fibrosis, tail-intravenous injection of miR-29a agomir would result in a significant reduction in TGF-β1 and CTGF content, the severity of pulmonary fibrosis, as well as the suppression of Smad3 expression in the nucleus." (PMID 39479511, 2024). "This study demonstrated that PRXT treatment could prevent bleomycin-induced pulmonary fibrosis in vivo and in vitro by regulating GRK2/Smad3 signaling pathway." (PMID 37815883, 2023). "Here, we also found that PRTX could inhibit GRK2 during pulmonary fibrosis, subsequently blocking the activation of TGF-β1/Smad3 pathway." (PMID 37815883, 2023). "Because TGF-β1 is one of the most potent activators of lung fibrosis, we determined that derrone inhibits the TGF-β-dependent Smad signaling pathway using SBE-luciferase activity and phosphorylation of Smad2 and Smad3." (PMID 37108428, 2023). "One previous study has reported that GRK2 levels were increased in lungs and isolated fibroblast cells during pulmonary fibrosis and GRK2 inhibition could decrease extracellular matrix (ECM) accumulation by downregulating Smad3 expression." (PMID 37815883, 2023). "To determine whether CAT played an important role in the TGF-β signaling pathway in pulmonary fibrosis, we measured the protein expression levels of TGF-β1, Smad2/3, p-Smad2, p-Smad3, Smad7 as well as Snail." (PMID 35685407, 2022). "In addition, lung fibrosis was alleviated by PFD through inhibiting profibrotic signalling pathways, including transformation growth factor‐β1 (TGF‐β1)/Smad3 pathway and mitogen‐activated protein kinase (MAPK) pathway." (PMID 35861038, 2022). "In addition, knockout of Smad3, or inhibition of phosphorylated Smad3 into the nucleus by polypeptide, inhibits TGF-β1-induced pulmonary fibrosis in mice." (PMID 35269498, 2022). "However, as both HCl- and NM-induced pulmonary fibrosis models exhibited a sex-related activation of canonical SMAD2 and SMAD3, suggesting that other isoforms of TGF-β are activated when mice are exposed to NM." (PMID 34072833, 2021). "H19 is upregulated via diminishing miR‐140 expression in fibrotic tissues from IPF patients and bleomycin‐induced pulmonary fibrosis in mice and TGFβ1‐induced HBE and A549 cells, in which the TGFβ/Smad3 signal pathway is involved in myofibroblast generation and extracellular matrix deposition." (PMID 33533071, 2021). "Smad3 gene knockout protects mice from TGF-β1- and bleomycin-induced pulmonary fibrosis." (PMID 33987189, 2021). "For example, SMAD3 is the main transcription factor for TGF-β1 signals and acting on TGF-β-mediated Smad2/3 signaling may prevent or treat pulmonary fibrosis in COVID-19-infected cases." (PMID 34539756, 2021). "In conclusion, curdione might attenuate the progress of pulmonary fibrosis and suppress the differentiation of fibroblast through TGF-β/Smad3 signaling." (PMID 32075634, 2020). "Consequently, neutrophil elastase activates the Smad2/Smad3/α-SMA pathway to induce myofibroblast differentiation and pulmonary fibrosis." (PMID 31905700, 2019). "By upregulating the expression level of NS5ATP9, TAF efficiently improved BLM-induced lung fibrosis by inhibiting the differentiation of fibroblasts into myofibroblasts and increasing ECM production as well as the expression of phosphorylated-Smad3, among other proteins." (PMID 31331325, 2019).